LINC00313 (long independently transcribed non-coding RNA 313)
Synonyms: formerly C21orf84; NCRNA00313
Gene: Long non-coding RNA gene on chromosome 21 (43,439,234 to 43,479,534, reverse strand). Ensembl gene ENSG00000185186.
Diseases named in the same sentence as LINC00313 in open-access papers:
LINC00313 is named in the same sentence as 14 diseases in open-access papers, as found by Europe PMC text mining. Sharing a sentence is not in itself a finding about the gene and the disease. The quoted sentences say what the papers report.
cervical carcinoma (2 papers, 2022 to 2024). A carcinoma arising from either the exocervical squamous epithelium or the endocervical glandular epithelium. "This is similar to the findings of another research team in osteosarcoma and cervical carcinoma, who found that patients with high LINC00313 expression had poorer overall and disease-free survival." (PMID 35575252, 2022). "Also, a pro-tumorigenic role of LINC00313 has been described in osteosarcoma and cervical carcinoma." (PMID 38332153, 2024).
glioma (2 papers, 2021 to 2024). A benign or malignant brain and spinal cord tumor that arises from glial cells (astrocytes, oligodendrocytes, ependymal cells). "Moreover, LINC00313 is upregulated in glioma and promotes tumorigenesis, via enhancing cell proliferation, migration and invasion." (PMID 38332153, 2024). "UPF1 appears to delay the degradation of Linc00313 and enhance the effect of Linc00313 on glioma." (PMID 33732285, 2021). "UPF1 and Linc00313 are both upregulated in glioma tissues and cells." (PMID 33732285, 2021). "Knocking down the expression of Linc00313 or UPF1 can inhibit the proliferation, invasion and migration of glioma cells, and promote apoptosis." (PMID 33732285, 2021).
osteosarcoma (2 papers, 2022 to 2024). A usually aggressive malignant bone-forming mesenchymal neoplasm, predominantly affecting adolescents and young adults. "High expression of LINC00313 was associated with shorter OS in osteosarcoma." (PMID 35575252, 2022).
papillary thyroid cancer (2 papers, 2021 to 2024). "LINC00313 is a lincRNA that possesses oncogenic properties and is a marker of poor prognosis in papillary thyroid cancer." (PMID 38332153, 2024). "SP1 specifically binds to the promoter region of linc00313, plays a role in promoting transcription, and enhances the proliferation, migration, and invasion ability of papillary thyroid cancer cells." (PMID 33542193, 2021).
head and neck squamous cell carcinoma (1 paper, 2024). A squamous cell carcinoma that arises from any of the following anatomic sites: lip and oral cavity, nasal cavity, paranasal sinuses, pharynx, larynx, and salivary glands. "Although LINC00313 is dysregulated in several tumors, its role in head and neck squamous cell carcinoma (HNSC) is not fully understood." (PMID 38617010, 2024).
hepatocellular carcinoma (1 paper, 2024). A malignant tumor that arises from hepatocytes. "LINC00313 was also highly expressed in hepatocellular carcinoma (HCC) cell lines HepG2 and Hep3B but TGFβ had no impact on its expression." (PMID 38332153, 2024).
liver cancer (1 paper, 2024). An epithelial or non-epithelial malignant neoplasm that arises from the liver. "In addition, a high expression of LINC00313 was observed in primary liver cancers (HCC and CCA) from the TCGA dataset (Fig. EV1C)." (PMID 38332153, 2024).
lung carcinoma (1 paper, 2022). "For example, LINC00313 was reported to be highly expressed in lung cancer and to indicate shorter overall survival (OS)." (PMID 35575252, 2022).
osteoarthritis (1 paper, 2023). A noninflammatory degenerative joint disease occurring chiefly in older persons, characterized by degeneration of the articular cartilage, hypertrophy of bone at the margins and changes in the synovial membrane. "Moreover, LINC00313 is down-regulated in OA, but the role of LINC00313 in the pathogenesis of osteoarthritis has not been explored." (PMID 36823651, 2023).
prostate carcinoma (1 paper, 2022). A carcinoma that arises from epithelial cells of the prostate gland. "BCYRN1 was reported to promote prostate cancer progression, and it is described as solely an oncogene, which is also the case of LINC00152, SNHG5 and LINC00313." (PMID 35205253, 2022).
tumor (3 papers, 2022 to 2024). "In total, 347 genes were upregulated and 327 genes were downregulated in LINC00313-overexpressing tumours." (PMID 38332153, 2024). "Interestingly, LINC00313 accelerated tumour growth in vivo when cells were xenografted in nude mice." (PMID 38332153, 2024). "Overall, LINC00313 appears to be more highly expressed in the late tumor stages." (PMID 38617010, 2024). "Our results suggested that LINC00313 might be involved in the tumor immune process and the expression level of LINC00313 might serve as a predictor of the response to tumor immunotherapy." (PMID 35575252, 2022). "In our study, the western blotting showed that LINC00313 might exert its tumor-promotive role by modulating EMT signaling, which was consistent with the results of cell invasion and migration." (PMID 35575252, 2022). "Thus, we suggest that LINC00313 positively regulates genes related to cell proliferation and stemness that could explain its effects on colony formation and CCA xenograft tumour growth." (PMID 38332153, 2024). "Although we did not detect LINC00313 over-expression in CCA tissues, the expression levels of ACTL6A, TCF7, WNT5A, AXIN2 and SULF2 were all increased in CCA human tumours (Fig. EV5B)." (PMID 38332153, 2024).
cancer (1 paper, 2024). A tumor composed of atypical neoplastic, often pleomorphic cells that invade other tissues. "KEGG pathway analysis revealed that many genes repressed after LINC00313 silencing are associated with cancer signalling pathways regulating pluripotency of stem cells, including the Wnt signalling." (PMID 38332153, 2024).
LINC00313 also shares sentences with these, for which no sentence is quoted: Kaposi's sarcoma (1 paper); testicular germ cell tumor (1).